IL1B (interleukin 1 beta)
Diseases named in the same sentence as IL1B in open-access papers (continued):
Sharing a sentence is not in itself a finding about the gene and the disease.
cystic fibrosis (continued). "In addition, AZM significantly reduces the expression of the proinflammatory cytokine IL-1β and the chemokine C-C motif ligand (CCL)-2 and TNF-α in M1-induced cystic fibrosis alveolar macrophages in patients with cystic fibrosis." (PMID 24632748, 2014). "Interestingly, the majority of P. aeruginosa isolated from cystic fibrosis patients with chronic airway infection are non-motile and T3SS-negative, suggesting that yet un-characterized inflammasome pathways regulate IL-1β production in cystic fibrosis patients." (PMID 30062052, 2018).
fibromyalgia (28 papers, 2009 to 2025). A chronic disorder of unknown etiology characterized by pain, stiffness, and tenderness in the muscles of neck, shoulders, back, hips, arms, and legs. "In the present study, circulating miRNA-223-3p expression levels were examined alongside VAS scores and IL-1β concentrations in individuals with fibromyalgia, revealing a significant association between miRNA-223-3p and pain severity." (PMID 41516054, 2025). "IL-1β's association with fibromyalgia pathophysiology has been the subject of both human and animal studies." (PMID 33042712, 2020). "Existing evidence on the role of miRNA-223-3p in regulating IL-1β production suggests that investigating this molecular interaction within the context of fibromyalgia may provide valuable insights into the mechanisms underlying chronic pain and inflammation." (PMID 41516054, 2025). "In similar, in the acid saline‐induced fibromyalgia model, there was an elevation observed in levels of IL‐1β and IL‐6." (PMID 40787071, 2025). "Increased levels of pro-inflammatory cytokines, such as TNF-α, IL-1β and IL-6 and their mediators, were detected in the suffering animals compared to the controls, confirming the key role of inflammation in fibromyalgia." (PMID 36979771, 2023). "The results of several studies have shown the presence of increased levels of IL-1β in patients diagnosed with fibromyalgia compared to controls, giving some support to this linkage." (PMID 33042712, 2020). "Recent research has demonstrated that CoQ10 attenuates NLRP 3 inflammasome activation and IL-1β serum levels in multiple acyl-CoA dehydrogenase deficiency (MADD) and fibromyalgia (FM) patients." (PMID 33381582, 2020). "Increased expression of NLRP3 and IL-1β was also found in blood of patients suffering from fibromyalgia, and treatment with coenzyme Q10 decreased both overexpression of NLRP3 as well serum IL-1β and IL-18 levels." (PMID 32973552, 2020). "Elevation of IL-1β, IL-6 and IL-8, and mast cells mediating microglia activation through the production of proinflammatory cytokines were found in patients with fibromyalgia." (PMID 33002009, 2020). "The evidence regarding IL-1β levels in fibromyalgia is highly inconsistent across literature." (PMID 41516054, 2025). "Conversely, some other studies have documented elevated IL-1β levels in fibromyalgia patients." (PMID 41516054, 2025). "In fibromyalgia (FM), serum levels of pro-inflammatory cytokines such as interleukin-6 (IL-6), interleukin-8 (IL-8), interleukin-1 beta (IL-1β), and tumor necrosis factor-alpha (TNF-α) are frequently elevated, whereas concentrations of anti-inflammatory cytokines are typically reduced." (PMID 41002443, 2025). "In addition, emerging research has demonstrated that CoQ10 attenuates NLRP 3 inflammasome activation and IL-1β serum levels in multiple acyl-CoA dehydrogenase deficiency (MADD) and fibromyalgia (FM) patients." (PMID 33381582, 2020). "However, protein levels of IL-1β are significantly higher in the culture supernatant of iMG cells from patients with fibromyalgia." (PMID 28928366, 2017). "Accordingly, the present study was designed as a pilot investigation aimed at comparing serum miRNA-223-3p and IL-1β expression levels, along with VAS scores, between fibromyalgia patients and healthy individuals." (PMID 41516054, 2025). "Despite the growing recognition of microRNAs in chronic pain mechanisms, no study to date has directly examined the relationship between serum miRNA-223-3p and IL-1β levels and pain severity (VAS scores) in patients with fibromyalgia." (PMID 41516054, 2025). "Proinflammatory cytokines such as IL-1β and TNF-α are elevated in fibromyalgia (FM), contributing to neuroinflammation and central sensitization, which amplifies pain perception and is linked to fatigue and cognitive dysfunction." (PMID 41002443, 2025).
fibromyalgia (continued). "For instance, mice with reserpine‐induced fibromyalgia exhibited a significant rise in proinflammatory cytokines like TNF‐α and IL‐1β in their bloodstream, which correlated with the increased activity of NLRP3 inflammasome." (PMID 40787071, 2025). "There was also a tendency for higher salivary IL-1β amounts in TMD patients, a finding that is supported by a previous study carried out with patients with TMD and fibromyalgia." (PMID 37471347, 2023). "Further, the release of IL-1β, IL-6, and TNF during moderate exercise has also been shown to be higher in patients with fibromyalgia than healthy controls." (PMID 26624891, 2015). "This may be related to overlapping inflammatory profiles, including elevated levels of IL-1β, IL-6, TNF-α, and IL-17, which are characteristic of FMF, CD, and fibromyalgia." (PMID 41451232, 2025). "Increases in CSF concentrations of IL-8, but not IL-1β, are consistent with fibromyalgia being mediated by glial cell activation in the central nervous system rather than prostaglandin-related pathways." (PMID 40002538, 2025). "Similarly, infliximab administration to rats with reserpine-induced fibromyalgia inhibited microglial stimulation via decreasing the expression of P2X7R and its downstream p38-MAPK, resulting in low levels of IL-1β, IL-6 and TNF-α." (PMID 37069462, 2023). "A decrease in TNF-α was not evident after SAP, SAP-SP, or HA treatment; this result might be explained by the fact that TNF-α is a less specific marker than IL-1β, considering that TNF-α levels in OA cannot be discriminated from that in fibromyalgia." (PMID 37143133, 2023). "In another pilot clinical trial, treatment with naltrexone resulted in marked inhibition of proinflammatory cytokines levels including IL-1β, IL-6 and TNF-α and reduction of fibromyalgia-associated nociplastic pain." (PMID 37069462, 2023). "The presence of ROS in fibromyalgia activates an inflammasome called NOD-like receptor family, pyrin domain containing 3 (NLRP3), which triggers the release of inflammatory cytokines, such as IL-1β and IL-18." (PMID 34239993, 2021). "Despite multiple favorable findings about the possible involvement of IL-1β in fibromyalgia, the results of some studies have not shown support of the bond between the levels of IL-1β and fibromyalgia." (PMID 33042712, 2020). "Although plasma cytokines were not analyzed in this study, muscle levels of IL-6 and IL-8 (but not IL-1β or TNF) were reported higher than plasma levels in patients with fibromyalgia, supporting that they are produced in the muscle." (PMID 28243900, 2017). "The role of central glial cell-mediated neuroinflammation is further supported by cerebrospinal fluid (CSF) studies, which demonstrate characteristic neuroinflammation patterns of increased interleukin (IL)-8 without consistent elevations in IL-1β in patients with fibromyalgia." (PMID 40002538, 2025). "Thus, this study indicates that IL-1β, IL-6, IL-8, and TNF do not seem to play an important role in maintenance of muscle pain in fibromyalgia." (PMID 26624891, 2015).
Infertility (28 papers, 2009 to 2025). "Local inflammation, caused by disordered vaginal microbiota, may lead to reduced levels of fertility; higher levels of cervical interleukin (IL)-1b, IL-6, and IL-8 cytokines have been reported to be associated with infertility." (PMID 35909180, 2022). "However, gonadotropin production can also be inhibited by the IL-1β cytokine, causing infertility." (PMID 37062827, 2023). "Higher cervical concentrations of the cytokines interleukin (IL)-1β, IL-6, and IL-8 have been observed in women with infertility and BV." (PMID 40652342, 2025). "Statistically increased IL-1β level (4.68 ng/L± 0.26) was noted in infertile males as compared to non-infertile males (3.24 ng/L ±0.24)." (PMID 37027384, 2023). "As expected, fertile men showed better sperm parameters as well as lower levels of NGF, F2-IsoPs, and IL-1β compared with men with infertility." (PMID 38137566, 2023). "Pro-inflammatory cytokine IL-1β was notably increased with statistical significance (p ≤0.05) in male infertile patients." (PMID 37027384, 2023). "By countering the functions of gonadotropins, IL-1β impairs follicle development and ovulation in a way that complements the actions of IL-1α, contributing to infertility." (PMID 37062827, 2023). "The mean values of IL-1β for all kinds of infertility are greater than the non-infertile group (3.24ng/L)." (PMID 37027384, 2023). "Based on this study, it appears that infertility in PCOS is directly related to the production of IL-1β with resultant inhibition of the gonadotropins FSH and LH." (PMID 37062827, 2023). "Factors that influence the incidence of infertility in adenomyosis are the increase of interleukin (IL-1β) and CRH expression." (PMID 36268444, 2022). "For example, PBMCs from Chlamydia-positive infertile women secreted more IL-6, IL-10 and IL-1β in response to Inc proteins than PBMCs from Chlamydia-positive fertile women." (PMID 24238294, 2013). "In contrast, IL-1β, IL-4, IL-5, IL-6, IL-10 mRNA expression levels were significantly higher (P < 0.05) in cells obtained from CT-positive infertile women compared to controls and CT-positive fertile women." (PMID 19698128, 2009). "It was previously discussed that IL-1β production is increased through HR caused by DHT excess, resulting in increased production of androgens and inhibition of gonadotropins; this further reinforces infertility in PCOS women." (PMID 37062827, 2023). "They reported increased β-glucuronidase activity, enhanced ERβ activity, and elevated levels of IL-1β and HIF-1α in infertile women with dysbiosis (defined as Lactobacillus spp < 90% in endometrial samples)." (PMID 41413507, 2025). "Although the activation of TLR4, and the expression of IL-1β and TNF-α, provides an essential host immune defence mechanism, they are also involved in different aspects of infertility." (PMID 32064024, 2020). "In this study we detected high levels of IL-1β, IL-6, IL-4, IL-5 and IL-10 in IncB or IncC-stimulated CD4+ T cells in CT-positive infertile women compared to CT-positive fertile women and controls." (PMID 19698128, 2009). "Significantly higher levels of IL-1β, IL-6 and IL-10 were secreted from IncB or IncC stimulated CD4+ T cells obtained from CT-positive infertile women as compared to CT-positive fertile women or controls (P < 0.05)." (PMID 19698128, 2009). "Cytokines like interleukin 1β (IL-1β), IL-6, IL-10, IL-18, tumor necrosis factor α (TNF-α), interferon g (IFN-g), and transforming growth factor β1 (TGF-β1) are notably elevated in idiopathically infertile males and those with varicocele." (PMID 40070583, 2025). "Among the objective parameters we examined with the data we obtained from our study, we investigated the effect of serum and sperm NLRP3, IL-1β, TAS, TOS, and OSI markers determining intracellular oxidative stress in infertile men with azoospermia and varicocele." (PMID 37476898, 2023).
Infertility (continued). "The fact that we found lower values of IL-1β in TFI patients indicates that impairment of folliculogenesis might have occurred and contributed to the infertility of these women." (PMID 22007253, 2012). "The ratio of IL1A or IL1B to IL10 decreased between Period 1 and 2 in infertile animals (P < 0.05)." (PMID 19476661, 2009). "Inflammasome mechanisms, such as NLRP3 and IL1-β molecules, may provide additional benefit in evaluating the need and benefit of surgical or medical treatment in infertility with and without vascular pathology and with and without azoospermia." (PMID 37476898, 2023). "Taken together, we provide evidence that a HFD decreased the IL1β level in mice-TIS and induced a high serum testosterone level, which reduced the physiologic germ cell apoptosis and increased the ratio of abnormal sperm that may be closely related to infertility." (PMID 28373640, 2017). "Pro-inflammatory cytokine IL-1β was significantly dysregulated while TNF-α and IL-6 were noticeably increased in infertile males, considering the possibility of cholinergic-mediated systemic inflammation in male infertility." (PMID 37027384, 2023).
lupus nephritis (28 papers, 2011 to 2025). Glomerulonephritis in the context of systemic lupus erythematosus. "Zhao and group discovered that decreasing NLRP3 recruitment and subsequent caspase-1 activity by blocking P2 × 7R, decreased glomerular damage in MRL/LPR mice with lupus nephritis, lowering serum anti-dsDNA antibody level, as well as IL-1β and IL-17 levels." (PMID 35204131, 2022). "We further demonstrated that citral inhibited ATP-induced caspase-1 activation and IL-1β production in LPS-primed J774A.1 macrophages and alleviated lupus nephritis in mice." (PMID 35967819, 2022). "There was a significant positive correlation between Hk2 and Hif1a and Il1b transcripts in MRL-lpr kidneys with lupus nephritis, implicating HIF1α-induced glycolysis in the induction of autoantibody-mediated inflammation in vivo." (PMID 32541026, 2020). "EGCG has been reported to inhibit NLRP3 inflammasome, and subsequently IL-1β expression in human umbilical vein endothelial cells exposed to palmitate, and lupus nephritis." (PMID 26866373, 2016). "Further analysis of inflammatory markers revealed that SAP treatment notably decreased systemic and local inflammatory cytokine levels of TNF-α, IL-1β, IL-6, IL-12, and MCP-1, which were closely associated with the severity of lupus nephritis." (PMID 21799927, 2011). "Neutrophil serine proteases act as alternative processing enzymes of pro-inflammatory cytokines IL-1β and IL-18 in vivo and modulate other inflammation-related control mechanisms such as progranulin inactivation in small vessel vasculitis and lupus nephritis." (PMID 21892962, 2011). "As a proinflammatory cytokine, IL-1β plays a critical role in the pathogenesis of glomerulonephritis, including immune complex glomerulonephritis, nephrotoxic serum nephritis, IgA nephritis, progressive crescentic glomerulonephritis, and lupus nephritis." (PMID 35888719, 2022). "Thus, we further detected serum levels of TNF-α and IL-1β in active lupus nephritis patients and normal controls." (PMID 26817892, 2016). "Moreover, recent research has revealed that human and murine macrophages, when stimulated by IgG immune complexes, undergo metabolic reprogramming dependent on mTOR and HIF-1α, resulting in the production of pro-inflammatory cytokine IL-1β, thereby promoting lupus nephritis." (PMID 39224584, 2024). "In lupus nephritis, activation of Nrf2 inhibits gene transcription of the NLRP3 inflammasome and inhibits the production of IL-1β, a downstream product." (PMID 35136484, 2022). "We found that CKD-506 significantly decreased levels of IFN-γ, IL-1β, IL-4, IL-6, IP-10, MCP-1, and CCL4 in the kidney extracts of mice with lupus nephritis." (PMID 30470828, 2018). "Lupus nephritis group had significantly higher levels of TNF-α and IL-1β compared to healthy controls (5.967 ± 2.402 ng/ml vs. 5.098 ± 1.072 ng/ml, P = 0.023; 6.213 ± 2.807 ng/ml vs. 4.441 ± 1.381 ng/ml, P = 0.001, respectively)." (PMID 26817892, 2016). "Among patients with SLE, those with lupus nephritis (LN) showed markedly elevated IL-1β levels compared with those without LN." (PMID 41624740, 2025). "However, quercetin reversed the expression of NLRP3, ASC, caspase-1, N-GSDMD, and IL-1β induced by IL-33, indicating that quercetin can relieve inflammasome- and GSDMD-mediated pyroptosis in the cellular model of lupus nephritis." (PMID 36421424, 2022). "Moreover, in lupus nephritis, GSK3 activates NLRP3 and therefore, IL-1β production, and psychological stress activating GSK3 induces the NLRP3/IL-1β pathway." (PMID 30174579, 2018). "In this study, antroquinonol, the major active component of ACE, inhibited the production of TNF-α and IL-1β in LPS-induced RAW 264.7 cells, suggesting that this anti-inflammatory activity may contribute to the function of ACE in attenuation of the progression of lupus nephritis." (PMID 18955361, 2011).
lupus nephritis (continued). "Moreover, in patients with lupus nephritis, a significant correlation was found between serum TNF-α concentration and serum PTX3 level (r = 0.351, P = 0.012), but not between IL-1β and PTX3 (r = 0.062, P = 0.861)." (PMID 26817892, 2016).